MED9 (mediator complex subunit 9)
Description:
Component of the Mediator complex, a coactivator involved in the regulated transcription of nearly all RNA polymerase II-dependent genes. Mediator functions as a bridge to convey information from gene-specific regulatory proteins to the basal RNA polymerase II transcription machinery. Mediator is recruited to promoters by direct interactions with regulatory proteins and serves as a scaffold for the assembly of a functional preinitiation complex with RNA polymerase II and the general transcription factors.
Synonyms: MED25; FLJ10193
Tractability: Small molecule: a structure with a bound ligand is known. PROTAC: ubiquitination databases record sites on it.
Gene: Protein-coding gene on chromosome 17 (17,476,994 to 17,493,221, forward strand). Ensembl gene ENSG00000141026.
Subcellular location: Nucleus
Subcellular location (Human Protein Atlas): Nucleoplasm; Midbody
Pathways (Reactome):
Developmental Biology: Transcriptional regulation of white adipocyte differentiation
Disease: RSV-host interactions
Metabolism: PPARA activates gene expression
Gene Ontology:
Molecular function: protein binding; transcription coregulator activity
Biological process: positive regulation of transcription elongation by RNA polymerase II; positive regulation of transcription initiation by RNA polymerase II; RNA polymerase II preinitiation complex assembly; regulation of transcription by RNA polymerase II
Cellular component: core mediator complex; nucleus; mediator complex; nucleoplasm
Genetic constraint (gnomAD): Loss-of-function variants: 8 observed, 13.34 expected, observed/expected ratio (o/e) 0.6, 90% interval 0.35 to 1.08. The upper end of that interval is the gene's LOEUF score, 1.08, which puts it in group 4 of 6, group 1 being the genes least tolerant of losing a copy. Missense variants: 180 observed, 202.4 expected, observed/expected ratio (o/e) 0.89, 90% interval 0.79 to 1.01. Synonymous variants: 87 observed, 86.15 expected, observed/expected ratio (o/e) 1.01, 90% interval 0.85 to 1.21.
Homologues: Orthologues: chimpanzee MED9 (99% identical), macaque MED9 (88% identical), dog MED9 (86% identical), guinea pig MED9 (86% identical), pig MED9 (77% identical), rat Med9 (76% identical), mouse Med9 (75% identical), tropical clawed frog med9 (43% identical), zebrafish med9 (41% identical), Drosophila melanogaster MED9 (24% identical).
Diseases named in the same sentence as MED9 in open-access papers:
MED9 is named in the same sentence as 4 diseases in open-access papers, as found by Europe PMC text mining. Sharing a sentence is not in itself a finding about the gene and the disease. The quoted sentences say what the papers report.
endometrial cancer (1 paper, 2025). Primary or metastatic malignant neoplasm involving the endometrium (mucous membrane that lines the endometrial cavity). "Of the gene-disease associations not reported previously, associations reaching exome-wide associations using all methods included MSH6 for endometrial cancer, ATM for prostate cancer, and MED9 (MIM: 609878) for melanoma." (PMID 40073867, 2025).
melanoma (1 paper, 2025). A malignant, usually aggressive tumor composed of atypical, neoplastic melanocytes. "Many of these associations were, however, based on low carrier counts, and the associations were less significant based on the more conservative Firth regression or a likelihood ratio test: of gene-disease associations not previously reported, only MED9 for melanoma reached exome-wide significance." (PMID 40073867, 2025).
cancer (1 paper, 2022). A tumor composed of atypical neoplastic, often pleomorphic cells that invade other tissues. "GEPIA2 database analysis of 33 cancer types showed the following top 10 ALKBH5-related genes: GID4 (R=0.71), TOP3A (R=0.67), MAPK7 (R=0.66), NT5M (R=0.61), FLII (R=0.59), ZNF18 (R=0.57), DRG2 (R=0.57), COPS3 (R=0.56), MED9 (R=0.56) and PRPSAP2 (R=0.56) (all P<0.0001)." (PMID 35444654, 2022).
MED9 also shares sentences with these, for which no sentence is quoted: prostate carcinoma (1 paper).